GPC1 (glypican 1)
Diseases named in the same sentence as GPC1 in open-access papers (continued):
Sharing a sentence is not in itself a finding about the gene and the disease.
tumor (continued). "Furthermore, the study found that the loss of expression of miR-96-5p and miR-149 is observed in both tumor tissues and plasma of CRC patients, as well as in GPC1-positive exosomes derived from CRC tumor tissues and plasma, before surgical treatment." (PMID 38298209, 2024). "In a recent study, mesothelin, mucin 4 (MUC4), annexin A10 (ANXA10), and glypican 1 (GPC-1) were observed to be selectively expressed in the tumor when compared to non-neoplastic pancreatic ducts and acini." (PMID 39062863, 2024). "Considering that GPC1 expression is also observed in the stroma of PDAC, it is important to assess the accumulation of GPC1 mAbs labeled with 89Zr or 211At in patient-derived tumor xenograft models before proceeding to clinical translation." (PMID 37827841, 2023). "Approaches that target the tumor stroma rather than cancer cells, e.g. glypican-1 on CAFs or tumor endothelial marker 8 (TEM8) on CAFs, endothelium and pericytes present as a promising approach moving forward." (PMID 37880707, 2023). "Using IHC score in individual LUSC tumor tissue as a reference, we found that the expression profiling of WNT7B, WNT5A, FZD7 and GPC1 could be divided into four sub-clusters." (PMID 35850748, 2022). "Mice treated with the targeted NPs showed greater inhibition of tumor growth than those treated with Au-NPs without the anti-GPC1 antibody." (PMID 36142190, 2022). "GPC1 mRNA and the GPC1 protein were scarcely expressed in the normal noncancerous pancreas, whereas in tumor tissues, 59.7% of samples showed positive expression." (PMID 34249755, 2021). "A substantial increase in the percentage of mitotic tumour cells was detected following GPC-1-ADC treatment but not in response to the control ADC." (PMID 32152502, 2020). "A dramatic increase in the percentage of mitotically active tumour cells was observed following GPC-1-ADC treatment but not in the control ADC." (PMID 32152502, 2020). "The mechanisms mediating the increase in tumor growth in mice injected with GPC-1 shRNA PC-3 cells are not fully known." (PMID 31391540, 2019). "The results showed that CLDN9, AK4, PC, GPC1, and SRD5A3 were upregulated in EC tissues compared to in normal endometrium tissues, whereas B4GALT1, GMPPB, B4GALT4, and CHST6 were downregulated in tumor tissues." (PMID 31807118, 2019). "Furthermore, silencing of GPC1 in breast cancer and PDAC cells leads to a decrease in tumor growth and an attenuation of mitogenic responses." (PMID 29721179, 2018). "C57BL/6 mice bearing murine GPC-1 transduced MC38 (MC38-mGPC1) or MCA205 (MCA205-mGPC1) were treated with mGPC1-CART, and antitumor effects, adverse effects, induction of endogenous tumor antigen specific T cells, and combination with anti-PD-1 Ab were evaluated." (PMID 30400835, 2018). "Intravenous administration of mGPC1-CART showed strong anti-tumor effects against GPC-1 transduced murine tumors in vivo without any overt adverse effects." (PMID 30400835, 2018). "Not surprisingly, when compared to the tumor marker CA 19-9 (AUC: ranging between 0.69 and 0.79), exosomal GPC1 was found to be significantly superior (p < 0.001)." (PMID 30671023, 2018). "Moreover, the secretion of GPC1+ exosomes was validated in the plasma of mice bearing HT‐29 and HCT‐116 tumours." (PMID 28233416, 2017). "Importantly, NCAN, as a component of extracellular matrix, is reported to bind to HSPGs including glypican-1 and syndecan-3 and FGF2 via its C-terminal domain, which was shown to be essential for tumor sphere formation in our experiments." (PMID 29290949, 2017). "Expression of GPC1 was higher in ESCC tumor tissues than in adjacent non-tumoral tissues and normal tissues." (PMID 28445969, 2017). "In addition, anti-GPC1 mAb also partially inhibited tumor growth in NOD/SCID mice, inhibiting tumor angiogenesis, suggesting that the possibility of the presence of neutralizing activity of GPC1 in this clone." (PMID 28445969, 2017).
tumor (continued). "Also, overexpression of miR‐96‐5p and miR‐149 significantly decreased the secretion of GPC1 positive exosomes from HT‐29 and HCT‐116 cells in vitro as well as xenograft HT‐29 and HCT‐116 tumours in vivo." (PMID 28233416, 2017). "Notably, while anti-GPC1 mAb seemed less effective in NOD/SCID mice than in SCID mice, it still showed tumor growth inhibition (38.7% ± 6.39) in TE14 xenografts in NOD/SCID mice compared with control mice treated with mouse IgG2a." (PMID 28445969, 2017). "These exosomes carry a large number of tumor-related proteins, such as EGFR, HER2, PD-L1, MET and GPC1, which may be used as cancer-specific markers; ii) a high level of stability, making them suitable for long-term storage and the detection of clinical samples." (PMID 40612948, 2025). "Therefore, GPC1 protein in the preoperative plasma is likely to be derived from surviving tumor cells rather than cells damaged by NAC." (PMID 39300946, 2024). "GPC1 is a glycosylphosphatidylinositol (GPI) anchored protein located at the plasma membrane, which regulates the biological activities of the fibroblast growth factor (FGF) family, such as embryogenesis, cell growth, morphogenesis, tissue repair, and tumor growth." (PMID 39300946, 2024). "We demonstrated that AT101 is able to: (i) specifically recognize GPC1-expressing cells; ii) specifically accumulate in the tumor microenvironment of a PDAC xenograft mouse model; iii) elicit a very strong immune response; iv) control tumor growth in the xenograft mouse model of PDAC." (PMID 38017492, 2023). "Person’s chi-square test indicated that the combined expression of ANXA2 and GPC1 was dramatically associated with age (P < 0.001), WHO grade (P = 0.005), recurrence (P < 0.001), and survival status (P < 0.001) but not with gender or tumor location." (PMID 33712571, 2021). "Thus, gpC1 expression seems to be tumor-specific but not histological type-dependent, reflecting perhaps its characteristics as a conserved epitope of oncofetal blood group precursor antigens." (PMID 32879924, 2020). "Since there are some reports that GPC-1 is reported to be shed into the extracellular matrix, and high GPC-1-expression tumours secrete a lot of GPC-1 and lead to high serum GPC-1 level, we might predict an effect of GPC-1-ADC by measuring the serum GPC-1 levels." (PMID 32152502, 2020). "Importantly, the affinity of MIL-38-CD3 for CD3 was 1000 fold lower than for GPC-1, an important feature for a BiTE, to minimise T cell binding in the absence of tumour cell recognition, and resultant toxicity." (PMID 33302918, 2020). "This suggests that crExos GPC1 could be useful at monitoring gross tumor burden, but not microscopic residual disease." (PMID 29721179, 2018). "Thus, GPC1 contributes to proliferative activity of tumour cells in the presence and absence of the α3(V) chain, although this ability is reduced in the absence of α3(V)." (PMID 28102194, 2017). "Notably, GPC1 has previously been reported to be expressed on tumor vascular endothelial cells but not on normal vascular endothelial cells." (PMID 28445969, 2017). "It is worth noting that, in this work, we report a decrease in the expression of GPC1 and an increase in GPC5 with increasing tumor grade, suggesting that the involvement of these molecules in cancer, as in the case of GPC3, may range from tumor suppressors to oncogenes depending on tumoral context." (PMID 24570896, 2014). "As ADCs undergo intracellular processing it is likely that the ADC will only act on the membrane bound GPC-1 protein, however there is potential that the ADC could bind to the soluble fragment found in circulating exosomes, which may limit the availability of ADC to target the tumor." (PMID 37880707, 2023).
tumor (continued). "In addition, magnetic resonance imaging in nude mice with an orthotopic PDAC tumor derived from BXPC3 showed a greater signal to the tumor site when the mice were treated with targeted Au-NPs compared with mice injected with Au-NPs without the anti-GPC1 antibody." (PMID 36142190, 2022). "However, whether GPC1 is also a specific marker for the exosomes of CRC tumours has not been addressed." (PMID 28233416, 2017). "Furthermore, analysis of the glypican 1 expression levels in the different tumors in relation to their diagnosis features showed a significant negative correlation with tumor grade (rs = −0.74, p < 0.0001), reflecting the disappearance of the expression in tumors of grade 2 or higher." (PMID 24570896, 2014). "The expression and stability of GPC1 were confirmed in modified PANC02 cells using Western blot and flow cytometry, indicating that GPC1 expression did not influence tumor cell growth." (PMID 40282924, 2025). "Anti-GPC1 human and murine CAR T-cells demonstrated antitumor effects in xenogeneic and syngeneic solid-tumor mouse models, with no obvious adverse effects." (PMID 38727261, 2024). "Interestingly, GPC1-enriched cirExos declined following PDAC resection, and a high cirExos GPC1 level was associated with a large tumor size, indicating that GPC1 might be associated with tumor burden and might not be a PDAC biomarker." (PMID 36980662, 2023). "Although the expression of miR‐182‐5p was elevated in the tumour tissues and GPC1 positive exosomes from CRC patients, its expression in the plasma and plasma GPC1+ exosomes was not significantly changed." (PMID 28233416, 2017). "In support of this possibility we found that, unlike FGF2, effects of the acidic FGF1 (pI≈6) on tumour cell proliferation were not affected by α3(V) ablation and that FGF1 did not bind α3(V)-NTD or GPC1 in immunoprecipitations." (PMID 28102194, 2017). "Moreover, the expressions of GPC-1, GPC-2, GPC-4, GPC-5, and GPC-6 were not significantly different between tumor and normal liver tissues." (PMID 33902495, 2021). "Therefore, whole-body evaluation using [89Zr]GPC1 mAb PET is an ideal method compared with biopsy from a single lesion or blood biomarker, because the former can assess only a portion of 1 lesion and the latter can provide averaged information irrespective of the overall tumor burden." (PMID 37827841, 2023).
cancer (168 papers, 2008 to 2026). A tumor composed of atypical neoplastic, often pleomorphic cells that invade other tissues. "Glypican-1 is overexpressed and has a diagnostic and prognostic value in multiple cancer types, including breast cancer, esophageal SCC (ESCC), glioma, and pancreatic cancer." (PMID 39797955, 2025). "Recently, increasing evidence has shown that GPC-1 is a cancer-associated protein that would aid in the detection and monitoring of cancer development." (PMID 38982153, 2024). "Further, clinical research and patient survival analyses reveal that high GPC1 levels are associated with poor prognosis in a number of cancers including glioblastoma, pancreatic adenocarcinoma, bladder urothelial carcinoma, and liver hepatocellular carcinoma." (PMID 38612755, 2024). "The results of the analyses unveiled a significant association between the GPC-1 gene and fundamental molecular pathways closely tied to cell cycle, actin cytoskeleton regulation, and cancer pathways." (PMID 37649964, 2023). "GPC1 has also been implicated in cancer cell proliferation, invasion, and metastasis, but its expression is low in normal human tissues." (PMID 37827841, 2023). "Although previous studies have shown that glypican 1 is associated with the activation of AKT in cancer cells, this is the first study to report AKT as a link between glypican 1 and eNOS in the lungs in physiological conditions." (PMID 37834029, 2023). "Survival analysis results revealed an association between high level of GPC1 expression and poor prognosis in several cancer types including BLCA, LGG, and LIHC." (PMID 36944188, 2023). "CD9, CD63, or glypican-1 can be taken into consideration as generic tumor-associated markers of exosomes produced by a major group of cancers." (PMID 35757760, 2022). "Collectively, these research data obtained with clinical samples greatly support the value of exosomal GPC-1 as a potential diagnostic marker for cancer screening." (PMID 35757760, 2022). "Heretofore, GPC3 and GPC1, which show excellent diagnostic effects in specific cancer types, respectively, have monopolized most studies of glypicans." (PMID 35345673, 2022). "Common EV markers (CD63, TSG101) and disease-specific EV-associated proteins (PD-L1, GPC-1) were readily detected following isolation by the ACE chip from either spiked EV or donor cancer samples." (PMID 33224932, 2020). "GPC1 expression in cancer is linked with malignant phenotypes such as promotion of cell-cycle and enhanced metastatic potential, and is considered as a prognostic factor in some cancers." (PMID 32228854, 2020). "Studies have shown that GPC-1 is abnormally expressed in a variety of tumor tissues and is associated with the cancer development." (PMID 31355137, 2019). "There are also other reports that employed various methodologies to evaluate the diagnostic potential of GPC-1 in cancers." (PMID 31355137, 2019). "In 2015, Nature published an article presenting a near-perfect diagnostic biomarker for PC – glypican-1 (GPC1) – a cell surface proteoglycan that is specifically enriched on cancer cell-derived exosomes." (PMID 29304816, 2018). "GPC1 is known to function as a co-receptor/modulator of various growth factors to enhance the binding to their respective receptors, and cancer-associated fibroblasts (CAFs) are an important contributor of some of those growth factors in tumors, including FGF2 and TGFβ." (PMID 38966167, 2024). "Our results indicate that GPC-1 might affect the development, prognosis, and therapy of cancers by associating with immune cells." (PMID 38982153, 2024). "In addition, survival prognosis, immune infiltration, and clinical phenotype analysis of GPC-1 expression in pan-cancer showed an association with its upregulated expression." (PMID 38982153, 2024).
cancer (continued). "Our study, based on the analysis of numerous databases, found that GPC-1 expression is upregulated in at least 12 common cancers and is associated with survival outcomes, as well as immune infiltration and clinical staging of several different types of cancer." (PMID 38982153, 2024). "In addition, it is possible that the accumulation of [89Zr]GPC1 mAb was observed in mouse-derived, cancer-associated fibroblasts present in the stroma of BxPC-3 GPC1-knockout tumors because of the expression of GPC1." (PMID 37827841, 2023). "Further investigations by KM survival analysis of GPC1 expression strata in these cancers unveiled correlation between high expression of GPC1 and poor prognosis pointing out the value of GPC1 as diagnostic tool or prognostic factor in these cancers." (PMID 36944188, 2023). "Moreover, in the context of PDAC, GPC1 expression has been detected in cancer-associated fibroblasts (CAF), which secrete the stroma." (PMID 36142190, 2022). "Indeed, the ability of GPC1 to modulate cellular adhesion and motility has been implicated in promoting the growth and angiogenic and metastatic potential of cancer cells in a variety of models." (PMID 32017809, 2020). "Moreover EVs are becoming increasingly important in monitoring cancer progression and therapy, since they are able to carry specific disease biomarkers such as Glypican-1, colon cancer-associated transcript 2, CD63, CD24, and many others." (PMID 31281356, 2019). "Circulating GPC-1 as a diagnostic and prognostic marker for cancer." (PMID 31355137, 2019). "Overexpression of GPC1 has been observed in both PC cell lines and tissues, and its expression level was closely related to the pathological grade and clinical stage of the cancer, and higher levels were associated with poor patient prognosis, suggesting its diagnostic and prognostic impact." (PMID 37304241, 2023). "A reported preclinical result supports the concept of using GPC1 as a cancer antigen for potential therapeutic regimens." (PMID 39797955, 2025). "A problem for implementation in a large population screening is the high technical requirements to isolate glypican-positive exosomes and the fact that glypican-1-positive exosomes are also found in other cancer entities." (PMID 39809756, 2025). "Pancreatic cancer, one of the deadliest cancer types, involves TEXs that carry the glypican-1 biomarker." (PMID 40182844, 2025). "Glypican-1 (GPC1) is a membrane-anchored protein that has been reported to be abnormally expressed in various cancers, suggesting its potential role in tumorigenesis." (PMID 40619414, 2025). "Genetic studies highlight glycerophosphocholine acyltransferase Gpc1’s role in PC remodeling, influencing cancer cell membrane dynamics through saturated/unsaturated PC balance." (PMID 40351532, 2025). "Careful selection of the appropriate EV subpopulations is imperative for the effective detection of the GPC1 protein and its corresponding mRNA as a cancer biomarker for PDAC." (PMID 38204202, 2024). "Taken together, combined GPC1 Exo‐mRNA/tMV‐mProtein expression holds significant promise for PDAC screening with a limited specificity for other cancer types." (PMID 38204202, 2024). "On the other hand, in various cancer studies, a secreted form of GPC1 has been reported to play additional roles in cancer biology." (PMID 39300946, 2024). "Recent studies showed that GPC-1 was aberrantly expressed and played an important role in certain cancers." (PMID 38982153, 2024). "Consistent with these previous studies, our research further showed that GPC-1 acted as an oncogene and promoted cancer progression in various tumors, especially HCC." (PMID 38982153, 2024). "We discovered that the expression level of GPC-1 in pan-cancer was obviously correlated with most immunosuppressive cells, such as CAFs and TAFs." (PMID 38982153, 2024).